CD4 (CD4 molecule)
Diseases named in the same sentence as CD4 in open-access papers (continued):
Sharing a sentence is not in itself a finding about the gene and the disease.
Autoimmunity (continued). "Th17 cell is one lineage of T helper cells originated from naive CD4+ T cells, and secretes pro-inflammation cytokines, such as IL-17A and IL-17F, participating in inflammatory response, autoimmunity, and transplant rejection." (PMID 36792629, 2023). "Given their potential to reduce the requirement for immunosuppression, CD4+CD25+FOXP3+ Tregs have been pursued for their therapeutic potential to suppress autoimmunity and to reduce or eliminate the requirement for immunosuppression after transplantation." (PMID 37874660, 2023). "CD4+ T-helper 17 (Th17) T cells are a key population in protective immunity during infection and in self-tolerance/autoimmunity." (PMID 37115755, 2023). "Another study delivered circumstantial evidence for autoimmunity associated with neurodegeneration in DLB patients, as CD4+ T cells were detected in postmortem brains near Lewy bodies." (PMID 39081998, 2023). "Some scholars also suggested that CD4+ T cells are the main driver of heart-specific autoimmunity in myocarditis." (PMID 37388276, 2023). "CD4+ T cells are essential for induction of AIH, whereas CD8+ T cells are linked to progression to fatal hepatic damage; in autoimmunity, where evidence of CD4+ T-cell co-stimulation is remarkable, that of CD8+ T-cell exhaustion is reduced." (PMID 37707595, 2023). "Cell death pathways play a central role in CD4 T cell-mediated diseases, including autoimmunity and cancer." (PMID 36901757, 2023). "In rodents, after MI, these cells have been reported to be accumulated early after injury in the damaged area, where they can activate FOXP3-CD4+ T helper cells and FOXP3+CD4+ regulatory T cells to prevent tissue-destructive autoimmunity." (PMID 37754786, 2023). "FOXP3+ regulatory T cells (Tregs) are a subset of CD4+ helper T cell lineages that function as a gatekeeper for immune activation and are essential for peripheral autoimmunity prevention." (PMID 35844606, 2022). "CAR CD4+ Tregs targeting organ-specific antigens suppressed autoimmunity in animal models of type 1 diabetes, multiple sclerosis and autoimmune colitis." (PMID 36405681, 2022). "Tregs are a population of immunosuppressive CD4+ T lymphocytes involved in maintaining immune tolerance to self-antigens and preventing autoimmune/autoinflammatory disease." (PMID 35478602, 2022). "Collectively, it is plausible that CD4+ Teff cells persistently reside in the PLNs and serve as a reserve force to damage β cells in the relapse of autoimmunity." (PMID 36091068, 2022). "The changes of the percentage of Tregs in CD4+ T lymphocytes and their suppressive activity can influence the progression of inflammation and autoimmunity." (PMID 36477951, 2022). "CD4 effector T-cell cluster 7 correlated inversely with autoimmunity to IA-2, while higher IL-10 response to the vaccine peptide associated with lower (i.e., improved) HbA1c values." (PMID 36505460, 2022). "Contrastingly, regulatory T cells constituting 5–10% of the peripheral CD4 + T cells have an important function in self-tolerance, inhibit antibody- and cell-mediated immunity responses and protect the host from autoimmunity." (PMID 36369088, 2022). "In RA, there is a notable increase in circulating and joint-localized Th1 and Th17 cells, essentially creating a CD4 T-cell phenotype indicative of chronic inflammation and autoimmunity." (PMID 35110573, 2022). "Other novel TNFR2 agonists are also being studied as potential therapeutic targets for treatment of autoimmunity and other inflammatory disorders and have been shown to expand highly suppressive CD4+Tregs capable of CD8+ T cell repression in vitro." (PMID 35874723, 2022). "Other studies have suggested that CD4+ CTLs contribute to the progression of autoimmunity and play a role in antitumor immunity." (PMID 35468944, 2022). "In this review, we summarized the current knowledge of glutamine catabolism in CD4+ T-cell subsets of autoimmunity." (PMID 36211442, 2022).
Autoimmunity (continued). "Together, we find that higher zinc doses impair the metabolic fitness of CD4+ T cells and prevent Th1 CNS autoimmunity and Th2 allergy." (PMID 35121767, 2022). "The therapeutic potential of TNFR2 agonists and antagonists has been progressively more studied in the context of CD4+Treg expansion or depletion in both autoimmunity, GvHD, and cancer." (PMID 35874723, 2022). "Continuous activation of antigen-presenting cells (APC), imbalances of regulatory and effector CD4+T cells, and high proliferation and activity of B cells which secrete a lot of antibodies combined with autoantigen ultimately lead to autoimmunity of LN." (PMID 35502341, 2022). "Recently, we discovered that pathogenic CD4 T cells were CXCR6 positive in experimental autoimmune encephalomyelitis (EAE), a commonly used Th17-driven autoimmune model." (PMID 35178050, 2022). "Previous studies have connected the genetic variation in the SH2B3/ATXN2 region with CD4+ T cells counts, and a variety of autoimmune conditions, including alopecia areata and sarcoidosis." (PMID 35386719, 2022). "CD4+Foxp3+ regulatory T cells (Tregs) play a crucial role in preventing autoimmunity and inflammation." (PMID 35603221, 2022). "If RTE CD4+ T cells in the neonate or perinate are hyper-responsive, why are young mice or children resistant to autoimmunity?" (PMID 36533239, 2022). "Immune phenotypes indicating autoimmunity were expected to present with lower CD4+/CD25+ co-expressing regulatory T cells (Treg)." (PMID 35337097, 2022). "Notwithstanding the limited size of a safety trial, we obtained the first evidence of antigen-pulsed tolDC to modulate islet-cell autoimmunity in vivo, predominantly targeting CD4+ T-cell responses and sparing general immune reactivity." (PMID 36505460, 2022). "In CNS autoimmunity, CD4+ T cells enter the subarachnoid space by crossing the blood–cerebrospinal fluid barrier and are reactivated by macrophages and dendritic cells into IL17+ T cells." (PMID 34979902, 2022). "ASyS appears to be characterized by CD4/T helper perturbations supporting B cell-mediated autoimmunity, while DM displays distinct alterations of the B cell compartment." (PMID 36291195, 2022). "For instance, CD4+ Foxp3+ regulatory T cells (Treg) protecting the body from autoimmunity and immunopathology have been shown to have a much higher ceramide content than CD4+ Foxp3− conventional (Tconv) T helper cells." (PMID 35997449, 2022). "While the role of CD4+ Tfh cells in autoimmunity is widely accepted, current data regarding a potential role for CD8+CXCR5+ follicular-like T cells are less clear and actually point to a dual role." (PMID 35406668, 2022). "As shown in the context of autoimmunity, CD4+ T cells are essential to initiate the immune responses that are subsequently dominated by CD8+ T cells during their later stages." (PMID 35657353, 2022). "IL-10-secreting T regulatory type 1 (Tr1) cells are an important subset of CD4+ T cells that control excessive inflammation and autoimmunity by inhibiting the functions of antigen-presenting cells and antigen-specific effector T cells." (PMID 36056390, 2022). "In recent years, with advances in research, the regulatory mechanism of CD4+CD25+Foxp3+Treg cells in the process of controlling autoimmunity and maintaining immune tolerance has been gradually understood." (PMID 35664563, 2022). "Regulatory T cells (Tregs), a subpopulation of CD4+ T cells that express transcription factor Foxp3, are central to the maintenance of immunological tolerance and prevention of autoimmunity." (PMID 35493450, 2022). "This soluble angiogenic factor was recently implicated in interactions between angiogenesis, Th17 polarization of CD4+ T cells and autoimmunity." (PMID 35794623, 2022). "The feasibility to isolate antigen‐specific CD4+ T cells by the sole use of phenotypic markers in CeD outlines a potential avenue for characterizing disease‐driving CD4+ T cells in autoimmune conditions." (PMID 35119226, 2022).
Autoimmunity (continued). "One of the studies showing the contribution of CD4+ Tfh cells in autoimmunity used the sanroque mouse model." (PMID 35406668, 2022). "Vice versa, regulatory CD4+ T cells down-modulate the macroautophagy machinery in dendritic cells to prevent autoimmunity." (PMID 35309359, 2022). "Together, our findings suggest that MBD2 directly binds to the methylated CpG DNA within the Stat1 promoter to suppress its transcriptional activity, thereby maintaining the homeostasis of the Th1 program in CD4 T cells to prevent organ-specific autoimmunity." (PMID 34420035, 2022). "ASyS was characterized by altered CD4 composition and expanded T follicular helper cells supporting B cell-mediated autoimmunity." (PMID 36291195, 2022). "CD4 cells play a vigorous role in the cardiac autoimmunity in myocarditis and CD8 cells have been shown to contribute to myocarditis gravity." (PMID 36358503, 2022). "Glutaminolysis inhibition of CD4+ T cells has an anti-inflammatory function in autoimmunity, promotes high levels of Foxp3 expression and decreases Th17 differentiation in SLE and EAE." (PMID 33717180, 2021). "Dendritic cells are crucial in the induction of adaptive immune responses and autoimmunity because of their unique ability of activating antigen‐specific CD4+ helper T cells." (PMID 33249764, 2021). "Th17 cells, a subset of CD4+ T cells, function as immune effectors in the setting of inflammation, infection, and autoimmunity." (PMID 33711076, 2021). "Converted polyclonal CD4+ T cells into FOXP3+ Tregs can be used in the context of autoimmunity or allogeneic responses." (PMID 33708227, 2021). "In contrast, other subsets that have strong implications for autoimmunity – namely, regulatory CD4+CD25+FoxP3+ Tregs – were reduced in knockout mice." (PMID 33737335, 2021). "Aging is shown to promote the ability of CD4+ T cells to generate an IL-17 response that promote autoimmunity in humans." (PMID 34872504, 2021). "Cell therapies, including mesenchymal stromal cells (MSC), have been shown to restore BBB integrity and augment endogenous splenic regulatory T cells (Treg), a subset of CD4+ T cells that function to regulate immune responses and prevent autoimmunity." (PMID 34038436, 2021). "Silencing of Clec16a protects against autoimmunity by inducing CD4+ T cell hyporeactivity, and CLEC16A expression is upregulated in peripheral APCs of MS patients." (PMID 33108502, 2021). "Foxp3+ Tregs are potent immunosuppressive CD4+ T cells that are critical to maintain immune quiescence and prevent autoimmunity." (PMID 34747370, 2021). "SATB1 in turn is predominantly expressed in CD4 + CD8 + lymphocytes exerting both activating and repressive regulatory functions implicated in autoimmunity and cancer." (PMID 34785669, 2021). "Mutant mice in which tyrosine at position 136 of LAT is replaced with phenylalanine (LatY136F mice) develop a lymphoproliferative disorder involving CD4+ T cell effectors that trigger systemic autoimmunity." (PMID 33125054, 2021). "First, through DRD3, dopamine favours the CNS-tropism in a pro-inflammatory B-cell subset with APC-function, thus contributing to the re-stimulation of encephalitogenic effector CD4+ T cells and thereby reinforcing CNS autoimmunity." (PMID 34920747, 2021). "First developed for cancer immunotherapy, CARs demonstrated their feasibility in early pre-clinical studies in which CD4+FOXP3+ Treg specificity was redirected against antigen relevant to autoimmunity." (PMID 33708227, 2021). "A subset of CD4 + lymphocytes, regulatory T cells (Tregs), are necessary for central tolerance and function as suppressors of autoimmunity against self-antigens." (PMID 33564037, 2021). "The depletion of CD25+Foxp3+CD4+ Tregs leads to autoimmunity while reconstituting this population prevents autoimmune disorders." (PMID 34068092, 2021). "Particularly CD4+ T cells, which secrete IL-17, are reported in autoimmunity wherein IL-17 development is promoted by cytokines IL-1 and TGF-β." (PMID 33429951, 2021).
Autoimmunity (continued). "CD4+ T cells play a pivotal role in the regulation of the immune system, protecting the host against various pathogens and autoimmunity." (PMID 34220854, 2021). "It is also known that CD73 is expressed in CD4 effector cells (anergic CD4 + T cells) to maintain autoimmunity in heathy tissue and to protect the fetus from maternal immunity during pregnancy." (PMID 34502315, 2021). "CD4+ FOXP3+ T regulatory (Treg) cells are key players in suppressing autoimmunity and maintaining self-immune tolerance." (PMID 34133541, 2021). "Protective autoimmunity depends on a particular CD4+ T cell response to specific neural autoantigens that, under certain conditions, protects, repairs, and restores nerve tissue instead of destroying it." (PMID 34203611, 2021). "Functional plasticity or conversion of CD4+ T cell into specific T-cell subset plays a critical role in induction and progress of autoimmunity." (PMID 34745114, 2021). "This study remains focused on the ability to restrain diabetogenic CD4+ T cells due to their importance in the initiation of autoimmunity." (PMID 34163475, 2021). "Treg is a subset of CD4+ T cells with potent suppressive functions necessary for theprevention of autoimmune conditions and reduction of inflammatory reactions via cell-cellcontact and secretion of soluble factors." (PMID 33650815, 2021). "Activating receptor NKG2D of CD4+ T cells showed anomalous appearances, with rising expressions in chronic inflammation and autoimmunity." (PMID 33808849, 2021). "Regulatory T (Treg) cells are a subtype of CD4+ T cells that play a significant role in the protection from autoimmunity and the maintenance of immune tolerance via immune regulation." (PMID 34239942, 2021). "CD4 + CD25+ T cells have been shown to be one distinct subset of regulatory T cells for the prevention of autoimmunity." (PMID 33933004, 2021). "In MDA5+/- mice, CB4 infection also results in increased regulatory Foxp3+ CD4+ T cells at the site of autoimmunity." (PMID 34804036, 2021). "Among T cell subtypes, autoimmunity has particularly been correlated with a reduction in Treg cells and an increase in T follicular helper CD4+ cells." (PMID 34290696, 2021). "This cytokine also promotes the specific differentiation of normal CD4+ T cells, which is necessary for T-helper 17 (Th17) to differentiate from simple CD4+ T cells, and is related to immune tolerance, autoimmunity and chronic inflammatory diseases." (PMID 34858386, 2021). "In this report, we provide novel evidence that pCons tolerance induces CD4+FoxP3+ T cells and potent regulatory B cells and granulocytes capable of suppressing autoimmunity in vitro in a murine model of SLE." (PMID 34093553, 2021). "With respect to identification of MHCII epitopes, the CD4 T cell repertoire to high affinity self-peptides is often deleted, tolerised or polarised to a regulatory repertoire as a mechanism to prevent autoimmunity." (PMID 34858415, 2021). "The Mir155 reporter assay in Th17 cells was used to screen FDA approved drugs with the intent to use these pre-existing drugs to treat autoimmunity as CD4+ Th17 cells express relatively high amounts of miR-155 relative to other CD4+ T cell subsets." (PMID 34075120, 2021). "While protecting against tumors and chronic infections, CD4+GranzB+CTLs also involve in the progression of autoimmunity disease." (PMID 34641948, 2021). "The results show that mice receiving Drd3-deficient or Drd3-sufficient CD4+ T cells developed EAE with similar kinetics and severity, thus ruling out a relevant role of DRD3 in CD4+ T cells in the development of CNS autoimmunity." (PMID 34920747, 2021). "Regulatory T cell (Treg) is a special CD4+ T cell subset that can maintain immune homeostasis, protect autoimmunity, and prevent excessive inflammation." (PMID 34912208, 2021).
Autoimmunity (continued). "In some of these cases, the role of BP180 specific CD4+T-cells was postulated as possible cellular mechanism of autoimmunity, especially in GvHD-like and lichen planus-like PAMS manifestations." (PMID 33995340, 2021). "T cells, CD4 + T cells and CD8 + T cells particularly, play a significant antiviral role by balancing the combat against pathogens and the risk of developing autoimmunity or overwhelming inflammation by adaptive immune responses." (PMID 33138692, 2020). "This is thought to result from reduced production of NADPH oxidase 2 (NOX2), which CD8+ Tregs release in exosomes to dampen CD4+ proliferation and resultant autoimmunity." (PMID 33117403, 2020). "CD4 T cells play a central role in mediating the host immune response to pathogens and in autoimmunity, cancer, and chronic inflammation." (PMID 33123017, 2020). "In general, both natural and induced immunoregulatory CD4+ T cells expressing the forkhead box P3 protein transcription factor (nFoxp3+Treg and iFoxp3+Treg, respectively) play a critical role in suppressing autoimmunity." (PMID 33603744, 2020). "Furthermore, a longitudinal study assessing the transition of naïve CD4+ T cells to activated memory autoreactive T cells from the blood of infants found that increases in IL-21 and Tfh gene signatures were associated with later development of β cell autoimmunity in children." (PMID 33262765, 2020). "Th17 cells provide critical support for immunity against extracellular bacteria and fungi and are the leading actors in autoimmunity, whereas Treg cells suppress the autoreactive activities of effector CD4+T cells and thus maintain immune tolerance." (PMID 32746780, 2020). "Regulatory T cells(Treg cells) belong to the unique subpopulation of CD4 + T cells that play a pivotal role in maintaining immune tolerance and preventing autoimmunity to self-antigens." (PMID 32970698, 2020). "CD4 Treg transfer before autoimmunity onset prevents autoimmune development, including autoimmunity within IL-Rβ-KO mice, which speaks to the importance of CD4 Tregs in preventing autoimmunity." (PMID 33319815, 2020). "As T helper (Th) type 1 response and IFN-γ levels are associated with autoimmunity and angiogenesis, in this study, we investigated the effects of TRS on dendritic cell (DC) activation and CD4 T cell polarization." (PMID 33178197, 2020). "Regulatory B cells (Bregs) and CD4+ regulatory T cells (Tregs) are subgroups of immunoregulatory cells involved in modulating autoimmunity, inflammation, and transplantation reactions." (PMID 33083479, 2020). "In particular, the membrane bound form of CD83 is absolutely essential for the development of CD4+ T cells and inhibits autoimmunity via the induction of regulatory mechanisms which dampen ongoing or overshooting immune responses." (PMID 32362900, 2020). "In this review, we focus on the understanding of the TCR-independent bystander activation of CD4+ T cells and the importance of bystander activation in potential immunological roles and therapeutic approaches during infection, autoimmunity, or cancer." (PMID 32859954, 2020). "Strong evidence revealed that Th17 cells represent a distinct subset of CD4+ T lymphocytes that plays a critical role in chronic inflammation and autoimmunity in mice." (PMID 32867778, 2020). "The second study provides evidence that homeostatic proliferation of pro-inflammatory CD4+ and CD8+CCR7-RA- or CD45RA+ memory T cells with a restricted T cell repertoire drives the risk for secondary autoimmunity." (PMID 32539719, 2020). "IL-17 is mainly released by Th17 CD4+ cells that are potent inducers of autoimmunity and are regulated by CTLA-4." (PMID 33162990, 2020). "Numerous studies have shown that CD8+ T cells modulate CD4+ T cell activation and proliferation in the setting of autoimmunity, transplant rejection, and anti-tumor immune responses." (PMID 32941545, 2020).